IGF1R (insulin like growth factor 1 receptor)
Diseases named in the same sentence as IGF1R in open-access papers (continued):
Sharing a sentence is not in itself a finding about the gene and the disease.
breast tumors (continued). "In another study, the expression of IGF-1R was analyzed in patients with recurrent breast tumors treated with tamoxifen for at least 6 months." (PMID 25680198, 2015). "Although IGF-1R expression was a worse prognostic factor in triple-negative breast tumors, it was a favorable prognostic factor in ER positive breast tumors." (PMID 24245483, 2013). "Expression of genes associated with this population may potentially be effective biomarkers of metastatic capacity in basal-like breast tumors with low levels of IGF1R expression." (PMID 42279332, 2026). "Moreover, the overexpression of IGF-1R provides breast tumors with an inherent resistance to radiotherapy and worsens the prognosis of patients." (PMID 36233084, 2022). "Similarly, inhibition of IGF-1R function using picropodophyllin (PPP) reduces breast tumor proliferation in the brain." (PMID 36556357, 2022). "To determine if cadherin expression similarly changes with IGF1R expression in patient tumors, we analyzed the METABRIC dataset and identified a positive correlation of E-cadherin with IGF1R expression but an inverse correlation of P-cadherin and IGF1R expression across all breast tumors." (PMID 36568144, 2022). "Our goal in this study was to use mouse models to test the hypothesis from the human data that low IGF1R in breast tumors directly contributes to a metastatic phenotype through dysregulated expression of specific cellular pathways." (PMID 36568144, 2022). "Interestingly, TCGA analysis of human breast tumors revealed a positive correlation between IGF1R and INSR expression." (PMID 36568144, 2022). "Interestingly, however, more recent evidence has emerged that suggests an additional, previously undescribed, tumor and metastasis suppressive function for IGF1R in both human breast tumors and mammary oncogenesis in mice." (PMID 35784559, 2022). "Overall, IGF-1R expression is upregulated in breast tumors to a varying degree across subtypes, with higher expression observed in luminal A and B tumors than in HER2+ and TN tumors, an association that is likely related to the regulation of IGF-1R expression by ER." (PMID 36556357, 2022). "However, targeting several other RTKs including the epidermal growth factor receptor (EGFR) and the insulin-like growth factor receptor (IGF1R) in breast tumors has been mostly unsuccessful." (PMID 36568144, 2022). "IGF1R bestows the stem cell characteristics and therapy resistance to breast tumors." (PMID 34528314, 2021). "Different studies have shown that up to 50% of breast tumors express the activated form of IGF1R." (PMID 34528314, 2021). "In this cotext, our study highlights that S100A7 may be considered as a novel angiogenic paracrine mediator of the IGF-1/IGF-1R action elicited in breast tumors." (PMID 33557316, 2021). "Given that overexpression of EGFR and ERBB2 by breast tumors predicts a poor prognosis, it might be possible in the future to predict response to IGF1R-directed therapy based on ERBB2/EGFR status." (PMID 32391121, 2020). "Finally, enhancement of the response to other IGF1R monoclonal antibodies by gemcitabine has been demonstrated in several cancers, including breast tumors." (PMID 32391121, 2020). "Abundant studies have highlighted a crosstalk between IGF-1R and ERα in breast tumor cells." (PMID 30692633, 2019). "We can speculate that IGF-1R could interact with the methylated form of ERα, which we demonstrated to be exclusively expressed in the cytoplasm of breast tumors." (PMID 30692633, 2019). "Higher insulin levels may give the tumor a growth advantage, as most breast tumors express the IGF-1R and IR-A, both of which are involved in proliferation and tumorigenesis and are associated with tumor progression." (PMID 31455425, 2019). "In the present study, we tested the hypothesis that attenuated IGF-1R function promotes tumor epithelial cell stress resulting in tumor stromal environment alterations to establish an aggressive phenotype in breast tumors." (PMID 30458886, 2018).
breast tumors (continued). "Recent DNA affinity chromatography-based proteomic analyses using nuclear extracts of breast tumor cells along with biotin-labeled IGF1R promoter fragments, followed by mass spectroscopy, led to the identification of a large set of IGF1R promoter-binding transcription factors." (PMID 27446805, 2016). "Our results indicate that CD24 expression in breast tumors may indicate sensitivity to anti-IGF1R therapy." (PMID 27179633, 2016). "IGF1 was expressed in 30% of breast tumors, IGF1R in 26%, IGFBP2 in 74%, and IGFBP3 in 32%." (PMID 25619494, 2015). "Alterations in IGF-2R levels due to genetic abnormalities in breast tumors may lead to modulation of BrCa tumorigenicity possibly via an IGF-1R depended manner." (PMID 25743390, 2015). "The aim of this study was to assess whether IGF-1R expression of breast tumors changes during neoadjuvant therapy and to study whether these changes were associated with survival." (PMID 25680198, 2015). "The existence of physical and functional crosstalk between IR isoforms and the homolog receptor IGF-1R was proven by the observation that in cells and tissues overexpressing both receptors, such as breast tumors and TCs, IR may heterodimerize with IGF-1R leading to the formation of HRs." (PMID 30513575, 2018). "These large, independent patient datasets, comprising 4972 breast tumors, suggested to us that GPER, IGF1/IGF1R signaling and blood vessel density (CD34) are correlated, and that GPER and IGF signaling may be linked to changes in the breast tumor microenvironment." (PMID 29212519, 2017). "In addition, immunohistochemical analyses of IGF1R levels in a collection of primary breast tumors derived from BRCA1 mutation carriers and non-carriers revealed a higher score in BRCA1-associated tumors compared to sporadic tumors." (PMID 28706506, 2017). "The same study found a correlation between IGF-1R protein levels and prolonged BCSS and association between IGF-1R mRNA expression and both relapse-free survival (RFS) and BCSS indicating a concurrence between IGF-1R mRNA and protein levels in primary breast tumors." (PMID 25743390, 2015). "Our findings identify miR-770-5p as a tumor suppressor in breast tumors, acting as a regulatory switch that targets key players such as EGFR, HER2, IGF1R, as well as downstream effectors including AKT, ERK, and mTOR." (PMID 39051060, 2024). "Accordingly, both depletion of FOXA1, and the chemical inhibition of IGF1‐R and AKT by MK‐2206, an AKT inhibitor in clinical trials for the treatment of breast tumors, in MCF‐7 cells all reduced the expression levels of each protein in the pathway." (PMID 36056637, 2022). "We established that the IGF-1/IGF-1R axis triggers STAT3-dependent transcriptional activation of S100A7, which acts as a paracrine mediator in the breast tumor microenvironment." (PMID 33557316, 2021). "Launched as an anticancer drug targeting specifically the IGF-1R autophosphorylation, PPT was shown to prevent the paracrine recruitment of fibroblasts and their activation as CAFs by breast tumor cells expressing c-Myc." (PMID 33364239, 2020). "A dual inhibitor of focal adhesion kinase (FAK) and insulin-like growth factor 1 receptor (IGF-1R), TAE226, was evaluated in a panel of cancer cell lines, MIA PaCa-2 human pancreatic tumor and 4T1 murine breast tumor models." (PMID 31215459, 2019). "IGF1R and TGFB1 were significantly overexpressed in the highest AHR-expressing group, but only in ERα-positive breast tumors (p = 0.0088 and p = 0.0035, respectively)." (PMID 29320557, 2018). "We first determined that GPER is co-expressed with IGF1R and with the vessel marker CD34 in human breast tumors (n = 4972)." (PMID 29212519, 2017). "Taken together these findings suggest that IGF1/IGF1R axis engages ERK1/2 and AKT signaling to trigger the activation of HIF-1α/GPER/VEGF transduction pathway in breast tumor microenvironment." (PMID 29212519, 2017).
breast tumors (continued). "Additionally, we discuss the role of IGF1R in stem cell maintenance and lineage differentiation and how these cell fate influences may alter the differentiation potential and cellular composition of breast tumors." (PMID 25964777, 2015). "The data described so far imply the IGF1‐R/AKT pathway in Tel activity on FOXA1 and ERα protein levels and function and correlate FOXA1 with cell sensitivity to Tel antiproliferative effect in breast and non‐breast tumor cell lines." (PMID 36056637, 2022). "Breast tumor cells, and not stromal cells, are thought to predominantly express higher levels of IGF-1R." (PMID 36556357, 2022). "Preclinical studies have shown that several dual IGF-1R/IR RTKi, including OSI-906 (linsitinib), BMS-554417, and BMS-754807, exhibit anti-proliferative and pro-apoptotic affects in breast tumor cells, and inhibit breast tumor growth in vivo when given alone or in combination with hormone therapy." (PMID 36556357, 2022). "To determine the potential molecular mechanisms by which NEDD4 promotes breast tumor growth and progression, we determined the expression of NEDD4 along with PTEN, IGF-1R, and p-Akt by IHC using a TMA that consisted of 148 samples of early-stage primary invasive breast cancer." (PMID 31856858, 2019). "Interestingly, in human breast tumor samples, GPER expression correlates with IGF1R and with the vessel marker CD34, corroborating the engagement of GPER and IGF1 system in breast tumor angiogenesis in breast tumor microenvironment." (PMID 29212519, 2017). "Interestingly, treating trastuzumab-resistant cells with metformin re-sensitizes cells by disrupting the ERBB/IGF1R complexes, again strongly suggesting that a combined therapy would hold promise for patients with ERBB2+ breast tumors." (PMID 25964777, 2015). "Expression of Claudin-4, EGFR, CAIX, GLUT-1 and IGF1R was assessed by immunohistochemistry on tissue microarrays composed of 97 paired primary breast tumors and their distant (non-bone) metastases." (PMID 25417118, 2014). "Interestingly, diverse studies have shown that GPER bridges together estrogenic signaling with IGF1R and IR-mediated action in the breast tumor microenvironment, independent of the ER status." (PMID 33364239, 2020). "In both datasets, a strong, positive correlation in expression was found between GPER and IGF1R, and between GPER and the microvessel density marker CD34, indicating that IGF1R and GPER may be involved in angiocrine regulation of the breast tumor microenvironment." (PMID 29212519, 2017). "One question that has not been well addressed is whether IGF-1R has distinct functions in breast tumors depending on other active signaling pathways and/or the specific mutation(s) or oncogene driving the tumor." (PMID 26106366, 2015). "The role of IR and especially IRA as an alternative to IGF-1R signaling in BrCa is highlighted by studies addressing a regulatory effect of IR in mammary tumorigenesis, increased proliferation of BrCa cells in response to insulin and upregulation of IRA isoforms in breast tumors." (PMID 25743390, 2015). "This ability of PTK6 could underpin its critical role in a subset of breast tumors which do not express substantial levels of ErbB receptor family kinases, but rather express high levels of both IGF-1R and PTK6." (PMID 20668531, 2010). "Our findings were substantiated in a cohort of breast tumors in which IGF-1R expression was positively correlated with ERα/Src and ERα/PI3K expression, hallmarks of nongenomic estrogen signaling, reinforcing the link between IGF-1R and mERα." (PMID 30692633, 2019).
glioblastoma (67 papers, 2005 to 2026). The most malignant astrocytic tumor (WHO grade IV). "This IGF1R de-repression determined the increased expression of IGF1R, promoting a cancer stem cell state and radiation resistance in glioblastoma." (PMID 38892104, 2024). "For example, it was shown that the expression of miR-15b suppresses the proliferation and invasion of glioblastoma cells by targeting Igf1r expression." (PMID 37686596, 2023). "Supporting the validity of this approach, we recently demonstrated that the IGF1R inhibitor, Linsitinib, targeted GSCs and displayed in vivo efficacy against glioblastoma xenografts." (PMID 36394953, 2023). "Although triplex formation was not studied, another study provided evidence that a ribonucleotide sequence can be used to form a potential triple helix to inhibit gene expression of the IGF1R gene in rat glioblastoma cells." (PMID 36323673, 2022). "Herein we explore the role of IGF1R intracellular localization by comparing two glioblastoma cell lines that differ only in their IGF1R capacity to translocate to the nucleus." (PMID 35574033, 2022). "ZKK-3 also inhibits insulin-like growth factor-1 receptor (IGF-1R) and insulin receptor (IR) kinases overexpressed by glioblastoma." (PMID 35214064, 2022). "To study the effects of a possible treatment for glioblastomas involving the inhibition of IGF1R signaling, we repeated the injection of immunodeficient mice with U87WT and U87Mut clones, and when a tumor developed, we treated the mice with OSI906." (PMID 35574033, 2022). "In adequacy with our findings, other studies showed similar results by suggesting an anti-proliferative role of miR-7-5p through targeting the EGFR, MAPK and IGF1R/Akt signaling pathways in different tumoral contexts, such as glioblastoma and tongue carcinoma." (PMID 34381564, 2021). "In glioblastoma multiforme, IGF1/IGF1R signaling promoted survival and suppressed apoptosis of glioblastoma cells through the PI3K/AKT pathway." (PMID 32851683, 2020). "For instance, in vivo studies have noted that the inhibition of IGF-1/IGF-2 sensitized pancreatic tumors to gemcitabine, whereas combined IGF-1R and CSF-1R inhibition significantly improved survival outcomes in mice with glioblastoma multiforme." (PMID 32512898, 2020). "The findings reveal the cellular window of IGF1R targeting and establish IGF1R as an effective target for the prevention and treatment of glioblastoma." (PMID 33173731, 2020). "In brain tumors, IGF1R is frequently activated in medulloblastoma, and INSR and IGF1R are frequently activated in glioblastoma." (PMID 31480400, 2019). "Western blot analyses were performed in order to determine the protein expression levels of PDGFR-α, PDGFR-β and IGF-1R in the glioblastoma cell lines utilized in our study." (PMID 30200644, 2018). "We have studied the effects of the PDGFR inhibitor JNJ-10198409 (JNJ) and the IGF-1R inhibitor picropodophyllin (PPP) in glioblastoma cell lines as well as in primary cultures derived from patients affected by this type of tumor." (PMID 30200644, 2018). "We determined the effects of the PDGFR inhibitor JNJ-10198409 (JNJ) and the IGF-1R inhibitor picropodophyllin (PPP) in glioblastoma cellular models." (PMID 30200644, 2018). "Recently, it was confirmed that IGF-1R is overexpressed in glioblastomas and has been identified as an independent prognostic factor that is characterized by shorter survival and was associated with a less favorable response to temozolomide." (PMID 29113409, 2017). "IGF-1R signaling is active in several CNS tumors including medulloblastoma and glioblastoma, and components of the pathway such as IGF-1R and IGF2 are amplified in up to 20% of DIPG." (PMID 25748921, 2015). "Synergistic inhibition of migration of hAT-MSCs toward glioblastoma-BTICs was also confirmed after double knock down of CXCR4 + IGF1R." (PMID 26076490, 2015).
glioblastoma (continued). "Inhibiting the IGF-1R pathway has been shown to reduce tumor progression and halt metastasis formation in animal models of Ewing’s sarcoma and glioblastoma." (PMID 25748921, 2015). "It has been shown that inhibition of IGF-1R expression or activity produces antiproliferative effects in glioblastoma." (PMID 24709958, 2014). "The activation of the AKT pathway is crucial for the sensitivity of glioblastoma cells to IGF-1R inhibitors." (PMID 24378652, 2014). "Further, we identified IGF-1R as a direct functional target of miR-503 which exerts important effects on glioblastoma cells." (PMID 24378652, 2014). "In fact, several studies show that inhibition of IGF-1R expression exerts antiproliferative effects in glioblastoma." (PMID 24709958, 2014). "Studies on other solid tumor types, most notably glioblastoma, indicate a role for IGF-1R upregulation in resistance to EGFR-targeted therapies." (PMID 21776391, 2011). "IGF-1R mediates resistance to anti-EGFR therapy in primary glioblastoma through the continued activation of the PI3K/AKT survival pathway." (PMID 21776391, 2011). "The IGV-001 is a type of cellular immunotherapy that requires the excision of the patient’s primary glioblastoma, followed by ex-vivo treatment with an anti-sense oligodeoxynucleotide against the insulin-like growth factor 1 receptor (IGF-1R) followed by irradiation (NCT04485949)." (PMID 40171253, 2025). "In glioblastoma, miR-603 regulated and inhibited the expression of IGF1R." (PMID 38892104, 2024). "Moreover, they established that the phosphorylated insulin-like growth factor-1 receptor (p-IGF-1R)/PI3K/AKT/mTOR signaling pathway was the target of Luteolin for reducing the migration of glioblastoma cells." (PMID 36992138, 2023). "Our results suggest that IGF1R nuclear localization may contribute to an aggressive phenotype in glioblastoma cells by increasing their motility and metabolism rather than stimulating their proliferation." (PMID 35574033, 2022). "For example, in the study of glioblastoma, WT1 may affect the viability and chemoresistance of glioblastoma cells in vitro by regulating the expression of the insulin-like growth factor 1 receptor (IGF1-R) Pathway." (PMID 34692659, 2021). "Likewise, Insulin-like growth factor 1 receptor (IGF-1R) signaling is very important for glioblastoma progression and development." (PMID 30200644, 2018). "In particular, signaling mediated by IGF-1R is essential for the development of glioblastoma." (PMID 30200644, 2018). "Therefore, PDGFR and IGF-1R signaling inhibition are promising strategies for the treatment of glioblastoma patients." (PMID 30200644, 2018). "Similarly, IGF1-R signaling has been described in glioblastoma, and findings from preclinical studies suggest favorable combination effects when IGF1-R inhibitors have been combined with other receptor tyrosine-kinase (RTK)-targeting agents." (PMID 27822457, 2016). "Possibly, the high expression of IGF-1R in this cell line might provide survival advantage(s) as suggested for glioblastoma cell lines." (PMID 22159423, 2012). "Research involving BC and glioblastoma multiforme (GBM) models has demonstrated that antisense oligonucleotides (AS-ODN) targeting IGF-1R can provoke anti-tumor immune responses." (PMID 39273251, 2024). "Also, elevated IGF-1/IGF-1R signaling could inhibit the apoptosis of different cells, such as glioblastoma cells and renal carcinoma cells." (PMID 33867995, 2021). "Signaling mechanisms initiated by PDGFR and IGF-1R are important in glioblastoma, and inhibition of the signal transduction pathways initiated by these receptors could be a useful alternative strategy for glioblastoma treatment." (PMID 30200644, 2018). "Therefore, signaling initiated by IGF-1R is important for glioblastoma progression and development." (PMID 24709958, 2014).